RAC1 (Rac family small GTPase 1)
Diseases named in the same sentence as RAC1 in open-access papers (continued):
Sharing a sentence is not in itself a finding about the gene and the disease.
cancer (continued). "This is the first study to provide evidence that the transmembrane protein EMP1 potentiates tumor metastasis in a mouse model via an underlying mechanism of Rac1 activation that in turn is responsible for promoting the invasive migration of cancer cells." (PMID 29867202, 2018). "Because the UPR was not responsible for the phenotype of ER-stress-sensitivity of RAC1-depleted cells, we turned our attention to RAC1/cancer-linked kinase signalling pathways PI3K/AKT/MTOR and RAF/MEK/ERK." (PMID 29329780, 2018). "Overexpression of β1 integrin and the associated upregulation of Rac1 are associated with cancer cell polarity reversal, presence of LNM, and poor DFS, and polarity reversal is an independent predictor of poor prognosis of breast IMPC patients." (PMID 29435106, 2018). "EMT is viewed as a critical aspect of tumor invasion and metastasis and Rac1 is implicated in promoting EMT in a number of cancers." (PMID 30261690, 2018). "The small GTPase protein Rac1 is a known regulator of cellular motility that is associated with migration, metastasis, and invasiveness of various cancers." (PMID 30966582, 2018). "We recently showed that TRAIL signaling via TRAIL-R2 promotes invasion and metastasis of KRAS-mutated cancers by activating Rac1/phosphatidylinositol 3-kinase (PI3K) signaling." (PMID 28212753, 2017). "Cytosolic CTNND1 drives E-cadherin-deficient cancer cell migration, invasion and metastasis through activation of Rho-family GTPases Rac1 and Cdc42 and inhibition of RhoA activity." (PMID 29228664, 2017). "Remarkably, this version of COSMIC also reports a new position mutated in cancer, Gln-173, which corresponds to a position that we have identified in our 3D modeling and functional analysis, as being essential in the control of Rac1 ubiquitylation." (PMID 28317937, 2017). "While activating mutations in RAC1/2/3 are rare, Rac hyperactivation is a common theme in many cancers including breast cancer." (PMID 28423521, 2017). "Abnormal Rac1 signaling is linked to a number of debilitating human diseases, including cancer, cardiovascular diseases and neurodegenerative disorders." (PMID 27442895, 2017). "As highlighted, similar to cancer, Rac1 is associated with both protective and promoting effects in neurodegenerative diseases." (PMID 27442895, 2017). "Having established the critical importance of amino acids in position 175 and 204 in the control of Rac1 ubiquitylation, we assessed the impact of cancer-associated mutations at these positions on anchorage-independent cell growth." (PMID 28317937, 2017). "Rac GTPases (Rac1/1b/2/3) have been implicated in cancer cell motility, survival, and proliferation." (PMID 28423521, 2017). "Rac1 has been implicated as a cell cycle regulator and is known to promote cancer cell proliferation and survival." (PMID 28410221, 2017). "It is well established that the hyper-activation of Rac1 signaling pathways is associated with numerous cancer-associated processes, including proliferation, motility, and survival, in multiple cancer cell types." (PMID 28410221, 2017). "This highlights the potential importance of EHop-016 and similar compounds in combating Rac1-mediated cancer metastasis, a major cause of death in cancer patients." (PMID 27442895, 2017). "Our analysis of cancer-associated mutations in HACE1 pointed to a critical role of the ANK domain in coordinating the association of HACE1 with Rac1 for its ubiquitylation by the HECT domain." (PMID 28317937, 2017). "It has, thus, been proposed that the observed loss of Mtss1 in a number of cancers contributes to increased metastasis through diminishing Rac1-mediated stabilization of cell-cell contacts." (PMID 27442895, 2017). "RAC1b is a hyperactive variant of the small GTPase RAC1 known to be a relevant molecular player in different cancers." (PMID 27127508, 2016).
cancer (continued). "Since an elevated level of expression and activity of this protein has been associated with cancer metastasis, direct regulation of Rac1 activity is a potential strategy employed in the treatment of certain cancers." (PMID 27725632, 2016). "It is thought that other migration-associated molecules play a role in cancer cell migration when Rac1 activity is inhibited." (PMID 25888632, 2015). "We recently reported a novel interaction between Bcl-2 and Rac1 and linked that to the ability of Bcl-2 to induce a pro-oxidant state in cancer cells." (PMID 26430964, 2015). "It is also possible that migration-associated molecules other than Rap1 play a role in cancer cell migration upon inhibition of Rac1 activity, or vice versa." (PMID 25888632, 2015). "Rac1 is a well-known regulator of adherens junction assembly whose increased activity in cancer is linked to perturbations of intercellular adhesion." (PMID 26555075, 2015). "It should be noted that although these events are regulated differently in different cancer types, some of them, for example, the RAC1 variant, were previously shown to have a role in cancer transformation and progression." (PMID 25908786, 2015). "In recent years, the Rac1/Cdc42 pathway has been extensively studied and implicated in cancer metastasis and EMT-mediated cell migration and invasion." (PMID 26462147, 2015). "This evidence suggests that the dysregulation of the Rac1 signaling pathway by miRNAs is an important mechanism underlying cancer metastasis, particularly in cancer cell migration and cell invasion." (PMID 25202416, 2014). "When PIK3CA and AKT1 are downstream effectors of RAS, both HRAS and RAC1 are RAS superfamily of small GTPases that cause cancer growth, invasion, and metastasis." (PMID 25356910, 2014). "In line with this, the formation of lamellipodia during carcinoma invasion has been linked to the α6β4/PI3K/Rac1 pathway." (PMID 24505282, 2014). "P-Rex1 is an exchange factor for the RhoGTPase molecule Rac1, which has been implicated in progression to metastasis in a number of cancer models." (PMID 23382862, 2013). "Since recent studies have implicated aberrant Rac1 and Cdc42 activity in human cancer, these Rho GTPases have been proposed as anticancer targets." (PMID 24040362, 2013). "ERBB4 activation markedly activated Rac1, which has well-established links to cytoskeletal dynamics and cell migration, and which is implicated in cancer cell invasion and metastasis." (PMID 23681745, 2013). "RAC1 F28L mutation (RACF28L) is a fast recycling mutation which has been implicated in several cancer associated cases." (PMID 24146998, 2013). "Unlike related members of the RasGTPase family, reports of activating mutations of RhoGTPases, such as Rac1, RhoA or Cdc42 are relatively rare in cancer." (PMID 23382862, 2013). "In cancer biology, aberrant levels of Rac1 signalling has been implicated in many aspects such as uncontrolled proliferation, as well as growth transformation, invasion, and metastasis." (PMID 23586025, 2013). "RhoA, ROCK1 and Rac1 proteins are GTPases that regulate F-actin and thereby regulate cancer cell migration and have been implicated in metastasis of several types of cancer including CRC." (PMID 23560089, 2013). "The ability of Rac1 to induce metastasis has been closely linked to mesenchymal type motility in cancer cell lines." (PMID 22689141, 2012). "The hubs, (Rac1, Cdc42, RhoA, and HRas) identified in the network are widely studied proteins due to their association with human cancers and core cellular processes." (PMID 23028658, 2012). "Increased activity of Rac1 and overexpression of Pak1 are associated with the progression of cancer, but most of the evidence has come from cell culture studies." (PMID 20426825, 2010). "Notably, RAC1 expression progressively increases with advancing clinical stage in ACC, BRCA, KIRC, LIHC, and PAAD, suggesting that RAC1 is associated with tumor progression in these cancers." (PMID 39898257, 2025).
cancer (continued). "Interestingly, RAC1-amp/gain was also significantly associated with aneuploidy in 29 out of 32 cancer types, including HNSCC (as indicated by orange boxes underneath the x-axis)." (PMID 39941730, 2025). "In most cancers, these properties of Rac1 are attributed to gain-of-function mutations in the Rac1 gene; however, in PCa, Rac1, like most other Rho family members, is rarely mutated, hence tumorigenesis may be attributed to associated regulatory proteins." (PMID 41301045, 2025). "Furthermore, the present study found that RAC1 was highly expressed in most cancers and closely associated with tumor pathological stages." (PMID 40904408, 2025). "However, as visualized by cBioportal, cancer genome sequencing reveals additional RAC1 hotspot mutations scattered across many different cancer types." (PMID 41109929, 2025). "While Rac1 mutations are observed, Rac1 hyperactivation resulting from overexpression, abnormal upstream inputs, and deregulated degradation is more common in human cancers." (PMID 38424547, 2024). "Ras-related C3 botulinum toxin substrate 1 (Rac1) is a promising emerging target due to its critical role in cancer progression, as its dysregulation has been reported to be implicated in various forms of cancer." (PMID 39161777, 2024). "Alterations in the activity of RAC1 are implicated in a range of diseases, including cancer." (PMID 40396280, 2024). "Since Rac1 hyperactivation in cancer cells frequently correlates with elevated expression and/or activation of Rac1-GEFs, we speculated that the ∆Np63α-mediated reduction of Rac1 activity could be associated with a reduction in the levels of upstream Rac-GEFs." (PMID 38191532, 2024). "Altered cellular metabolism and increased glycolysis are well-known characteristics of cancer cells, and the association of RAC1 with altered metabolism in CRC could provide another CRC treatment avenue." (PMID 39001533, 2024). "Notably, this study addressed a potential targeted therapeutic strategy for cancers associated with CGN c.3560C > T by using the specific inhibitor NSC23766 to inactivate Rac1." (PMID 38424547, 2024). "Similarly, RAC1 was found to be implicated in the regulation of cell migration and metastasis of several cancer types." (PMID 39409902, 2024). "Loss of CYRI-B could therefore lead to hyperactivation or inappropriate spatial control of RAC1 activation causing a loss of normal cell polarity and therefore enhancing preneoplasia and cancer progression." (PMID 38712822, 2024). "Mutations in the Rac1 gene have been associated with various types of cancers." (PMID 39161777, 2024). "In this report, we showed for the first time that CBX3 gene amplification strongly co-occurs with both EGFR and RAC1 genes in different human cancers and that this molecular event is associated with an increase of mRNA and protein levels of CBX3, EGFR and RAC1." (PMID 37633946, 2023). "Moreover, TLR signaling by invading pathogens or during cancer-associated inflammation, activate Rac1 and Cdc42 which leads to Nuclear Factor kB (NFκB) transcriptional activity and secretion of inflammatory cytokines such as interleukin-6 (IL-6)." (PMID 37397366, 2023). "Except for BAI1, CD31, and MerTK, the enhanced expression of Axl, Tyro3, Gas6, MFGE8, Stab2, Tim-4, CX3CL1, IDO1, Rac1, and PD-L1 was associated with decreased sensitivity to many drugs, which may partially explain the resistance to chemotherapy in cancers." (PMID 36059952, 2022). "Previous studies have also shown that TIAM2 enhances the proliferation, migration, and invasion of LC cells as TIAM2 is not only an important receptor tyrosine kinase effector for Rac1-dependent cell motility, but also can affect cancer cells via cancer-associated fibroblasts." (PMID 36142328, 2022). "The gain-of-function (GOF) mutation of Rac1 can lead to cancer-related phenotypes." (PMID 35031595, 2022).
cancer (continued). "Since both RAC1 and RAC1b have been implicated in driving migration/invasion and malignant progression in several carcinomas, including PDAC, it is suggested that ALK2, in order to suppress cell migration and invasion, downregulates the abundance of the RAC1 and RAC1b proteins." (PMID 36289908, 2022). "RAC1 activating mutations have been found in several cancers." (PMID 34373577, 2021). "RAC1 activity has been widely linked to the regulation of cell invasion in cancer." (PMID 34667203, 2021). "In order to verify that the investigated effects of resveratrol on the growth of CAL-27 cells were associated with RAC1 inhibition, cancer cells were treated with RAC1 inhibitor (NSC23766) and agonist (DAM) for 4 h and then incubated with 20 μΜ resveratrol for 48 h." (PMID 34176441, 2021). "Hence, it is obvious that the number of RAC1 mutations and the mechanism of perturbations in RAC1 expression should be clearly studied to design new drugs for cancer patients." (PMID 34771549, 2021). "In addition to these well-known Rac1 Q61L and G12V mutations, several other ‘activating’ mutations of Rac1 have been identified, a.o. in cancer patients." (PMID 34252134, 2021). "Furthermore, RAC1 had been the only gene associated with histological type analyzing carcinomas of all dogs." (PMID 34679042, 2021). "In addition to NF-κB, other stress proteins, such as p38 and JNK, have been implicated as downstream effectors in RAC1-mediated pro-invasive, migratory signaling in cancer cells." (PMID 32545340, 2020). "In cancer, Rac1 and Cdc42 are mutated, overexpressed and (or) hyperactivated." (PMID 32322580, 2020). "Regarding cellular metabolism, Rac1 has been widely associated with macropinocytosis, a mechanism of endocytic uptake of extracellular fluid that assists in meeting the increased demand of nutrients required for cancer cells to proliferation." (PMID 32158759, 2020). "The present study revealed that pathogenic IDH1 mutation contributes to cancer aggressiveness via prompting cellular food-seeking, motility, chemotaxis, and endocytosis, which resulted from the augmented mTORC2/Rac1 pathway and concomitant cytoskeleton mobilization." (PMID 32224866, 2020). "Our study provided proof-of-concept evidence that targeting the mTORC2/Rictor/Rac1 pathway could be useful to treat IDH1-mutated cancers." (PMID 32224866, 2020). "Ras-related C3 botulinum toxin substrate 1 (RAC1) overexpression has been implicated in multiple cancer cell phenotypes associated with tumor progression, metastasis, therapeutic resistance, and an overall worse prognosis for patients across a variety of solid tumors." (PMID 32545340, 2020). "Rac1B is a cancer-associated fast-cycling splice variant of Rac1." (PMID 31330900, 2019). "As Rac1 exerts several physiological functions, alterations of its signaling are implicated in many diseases, such as cancer, cardiovascular disease, arthritis, kidney disorders, pathological inflammatory responses, infectious diseases, and neurodegenerative disorders." (PMID 31035701, 2019). "Rac1 is a driver of numerous cancer-relevant phenotypes associated with worse patient outcomes." (PMID 31344967, 2019). "Ras-related C3 botulinum toxin substrate 1 (Rac1) belongs to the Rho family of small GTPases and plays a central role in cytoskeleton organization and migration and as such has been associated with cancer invasion." (PMID 31857649, 2019). "Finally, triggering of formation of filopodia and dissolution of stress fibers were tested for another cancer-associated Rac1 mutant, Rac1/P29S." (PMID 31330900, 2019). "The p38 MAPK and the Rac1 signaling were also associated to SSc fibrosis and to cancer progression." (PMID 30866419, 2019). "Furthermore, the IPA results indicated that GINS4 is implicated in cancer cell proliferation, cell cycle, apoptosis and metastasis through Rac1 and CDC42 and their downstream signaling pathways: MAPK/ERK pathway, PI3K/AKT pathway and PTEN pathway." (PMID 31754397, 2019).
cancer (continued). "Thus, RAC1 is a Tier 1 cancer-causing gene and the mutational patterns in Rac1 are similar to many well-known oncogenes which are positive drivers of cancer." (PMID 30261690, 2018). "In addition, Rac1 has been reported to be associated with proliferation of cancer cells, partially by regulating cell cycle progression." (PMID 29534468, 2018). "We further investigate cancer-associated kinase signalling pathways and show that RAC1 knockdown reduces the activity of AKT and ERK, and using a panel of clinically important kinase inhibitors, we uncover a role for MEK/ERK, but not AKT, in cell viability under ER-stress." (PMID 29329780, 2018). "On the contrary, fast cycling P29S, P29L, and P29Q mutations in Rac1 have been identified by high‐throughput sequencing of clinical human cancers 104, 105, 106, the G17V RhoA mutation frequent found in T cell lymphomas 107, 108 and the Y42C RhoA mutation recurrently in diffuse gastric cancer." (PMID 29749605, 2018). "Rac1b is a constitutively active splice variant ot Rac1 overexpressed in breast and other cancers." (PMID 28423521, 2017). "However, some cancer cells upregulate TRAIL-R expression, and we recently showed that this facilitates progression of KRAS-mutated cancers via cancer cell-autonomous Rac1 activation independently of FADD." (PMID 28212753, 2017). "Mutation of proline 29 in the switch I region of Rac1 is a hotspot for cancer-linked mutations." (PMID 27304967, 2016). "Deregulation of Rac1 signaling has also been linked to a number of diseases, including cancer." (PMID 27152953, 2016). "Here, we examined whether Tβ4 expression is associated with activation of Rac1 and Rap1, and the effect of this association on the crosstalk between Rac1 and Rap small GTPases in terms of cancer cell migration and tumor metastasis." (PMID 25888632, 2015). "Tβ4-mediated Wnt signaling pathways could be also associated with Rap1 activation in Rac1-inhibited cancer cells." (PMID 25888632, 2015). "These TAK1-deficient cancer cells adopt a more mesenchymal morphology characterized by a higher number of focal adhesions, increased surface expression of integrin α5β1 and active Rac1." (PMID 25849436, 2015). "Aberrant Rac1 activation associated with c-Src activation, contributes to the development and progression of a variety of cancers, and is accompanied with poor prognosis, cancer invasion and metastasis." (PMID 25860930, 2015). "Therefore, we propose that by repressing Pak1 expression, Rb prevents Rac1 hyperactivity usually associated with cancer and related to cytoskeletal derangements that disrupt cell adhesion, consequently enhancing cancer cell migratory capacity." (PMID 26555075, 2015). "Another RAC1 mutation F28L has also been observed in several cancer cases." (PMID 24146998, 2013). "ERK has been implicated in the Rac1 signaling pathway in various human cancer cell lines." (PMID 22701712, 2012). "This might explain why Rac1 is constitutively activated in Bcr-Abl transformed cells, whereby Rac1 is implicated in increased motility of the cancer cells." (PMID 19426560, 2009). "Thus, in addition to its ability to reduce the activity of wild-type RAC1 and cancer-associated RAC1 P29S and RAC1b, A41 may also be able to reduce a range of situations where RAC1 is upregulated by GEF mutations in cancers." (PMID 40633540, 2025). "RAB4A suppression leads to the loss of cancer cell sphere formation in vitro and loss-of-tumor formation in both subcutaneous and orthotopic xenograft mouse models; this loss of tumorigenesis can be rescued by exogenous expression of constitutively active RAC1 (RAC1CA)." (PMID 39463384, 2024). "Similar to the other Rho GTPases, Rac1 could causes chemoresistance in various kinds of cancers." (PMID 33604328, 2020). "Hence, DOCK1 inhibition could be an approach for the treatment of cancers associated with the Rac1 P29S oncogenic mutation." (PMID 32322580, 2020).